IRF4 (interferon regulatory factor 4)
Description:
Transcriptional activator. Binds to the interferon-stimulated response element (ISRE) of the MHC class I promoter. Binds the immunoglobulin lambda light chain enhancer, together with PU.1. Probably plays a role in ISRE-targeted signal transduction mechanisms specific to lymphoid cells. Involved in CD8(+) dendritic cell differentiation by forming a complex with the BATF-JUNB heterodimer in immune cells, leading to recognition of AICE sequence (5'-TGAnTCA/GAAA-3'), an immune-specific regulatory element, followed by cooperative binding of BATF and IRF4 and activation of genes.
Synonyms: LSIRF; MUM1; IMD131; NF-EM5; SHEP8
Tractability: PROTAC: ubiquitination databases record sites on it; its protein half-life has been measured.
Gene: Protein-coding gene on chromosome 6 (391,739 to 411,443, forward strand). Ensembl gene ENSG00000137265.
Subcellular location: Nucleus; Cytoplasm
Subcellular location (Human Protein Atlas): Nucleoplasm; Cytosol
Pathways (Reactome):
Immune System: Interferon alpha/beta signaling; Interferon gamma signaling; Interleukin-4 and Interleukin-13 signaling
Developmental Biology: Differentiation of naive CD4+ T cells to T helper 2 cells (Th2 cells); Regulation of MITF-M-dependent genes involved in pigmentation
Disease: Nuclear events stimulated by ALK signaling in cancer
Gene Ontology:
Molecular function: DNA-binding transcription activator activity, RNA polymerase II-specific; protein binding; RNA polymerase II cis-regulatory region sequence-specific DNA binding; sequence-specific double-stranded DNA binding; DNA-binding transcription factor activity; DNA-binding transcription factor activity, RNA polymerase II-specific; sequence-specific DNA binding; cis-regulatory region sequence-specific DNA binding; transcription cis-regulatory region binding; transcription coactivator activity
Biological process: positive regulation of DNA-templated transcription; positive regulation of interleukin-10 production; positive regulation of interleukin-13 production; positive regulation of interleukin-2 production; positive regulation of interleukin-4 production; positive regulation of transcription by RNA polymerase II; defense response to protozoan; immune system process; positive regulation of cold-induced thermogenesis; regulation of T-helper cell differentiation; regulation of transcription by RNA polymerase II; T cell activation; T-helper 17 cell lineage commitment; positive regulation of multicellular organismal process; regulation of DNA-templated transcription
Cellular component: cytoplasm; membrane; nucleoplasm; nucleus; chromatin; cytosol; nucleosome
Genetic constraint (gnomAD): Loss-of-function variants: 11 observed, 47.54 expected, observed/expected ratio (o/e) 0.23, 90% interval 0.14 to 0.38. The upper end of that interval is the gene's LOEUF score, 0.38, which puts it in group 1 of 6, group 1 being the genes least tolerant of losing a copy. Missense variants: 386 observed, 577.88 expected, observed/expected ratio (o/e) 0.67, 90% interval 0.61 to 0.73. Synonymous variants: 241 observed, 236.03 expected, observed/expected ratio (o/e) 1.02, 90% interval 0.92 to 1.14.
Gene-disease validity (ClinGen):
ClinGen rates the evidence that IRF4 causes each of these diseases.
combined immunodeficiency (autosomal dominant): Definitive.
Homologues: Orthologues: chimpanzee IRF4 (99% identical), macaque IRF4 (98% identical), dog IRF4 (95% identical), rabbit IRF4 (95% identical), guinea pig IRF4 (93% identical), mouse Irf4 (92% identical), rat Irf4 (92% identical), pig IRF4 (86% identical), tropical clawed frog irf4 (71% identical), zebrafish irf4a (64% identical). Paralogues in human: IRF8 (41% identical), IRF5 (31% identical), IRF6 (28% identical), IRF9 (28% identical), IRF7 (24% identical), IRF3 (23% identical), IRF1 (17% identical), IRF2 (16% identical).
Diseases named in the same sentence as IRF4 in open-access papers:
IRF4 is named in the same sentence as 270 diseases in open-access papers, as found by Europe PMC text mining. Sharing a sentence is not in itself a finding about the gene and the disease. The quoted sentences say what the papers report.
myeloma (161 papers, 2009 to 2026). "BCL 6 (lymphoma-associated transcription factor), MUM1/IRF4 (multiple myeloma ocongene-1/interferon regulatory factor 4), and MIB1/Ki-67 (marker of cellular proliferation) are tumor markers associated with a higher risk for disseminated disease." (PMID 41189780, 2025). "Using a loss-of-function, RNA-interference-based genetic screen, IRF4 inhibition was reported to interfere with survival of several myeloma cell lines." (PMID 36495369, 2023). "Transcription factor PU.1, encoded by gene SPI1, acts as tumor suppressor for myeloma cells through direct transcriptional repression of IRF4." (PMID 35338347, 2023). "In multiple myeloma (MM), four Supertarget genes encode transcription factors such as interferon regulatory factor 4 (IRF4), PR/SET domain 1 (PRDM1), POU class 2 homeobox associating factor 1 (POU2AF1), and myocyte enhancer factor 2C (MEF2C)." (PMID 37297004, 2023). "Faulty regulation of IRF4 expression is associated with numerous lymphoid malignancies, including multiple myeloma (MM), an aggressive and incurable hematologic cancer characterized by the abnormal proliferation of bone marrow plasma cells." (PMID 35544413, 2022). "By using an appropriate targeting guide RNA, this time we focused on the IRF4 locus, which encodes Interferon Regulatory Factor 4, a transcription factor with critical roles in immune responses and in multiple myeloma." (PMID 35022246, 2022). "What is more, studies showed IRF4 dysregulation is associated with resistance to immunomodulatory compounds in Waldenström’s macroglobulinemia and myeloma." (PMID 33629212, 2021). "With a loss of function genetic screen, IRF4 is identified to be required for myeloma cell survival through activating its direct target MYC." (PMID 34680233, 2021). "IRF4 overexpression is a hallmark of activated B-cell-like type of diffuse large B-cell lymphoma and associated with classical Hodgkin lymphoma (cHL), plasma cell myeloma and primary effusion lymphoma." (PMID 34220922, 2021). "At the same time in plasmablasts, and in myeloma cell lines, IRF4 acquires a new association with the occupancy pattern of CTCF, suggesting a potential role in chromatin looping." (PMID 32843533, 2020). "By contrast, in myeloma cell lines, IRF4 occupancy was linked to ISRE, EICE, and CTCF motifs (MM_Comb)." (PMID 32843533, 2020). "Interferon regulatory factor 4 (IRF4) was identified as a myeloma-associated proto-oncogene transcriptional factor." (PMID 31167518, 2019). "Polymorphisms in the IRF4 gene contribute to elevated IRF4 expression in cells from patients with multiple myeloma." (PMID 31178872, 2019). "Another example is variants in CRBN (cereblon) and IRF4 that are involved in myeloma risk and additionally affect therapy responses." (PMID 31139207, 2019). "IRF4 polymorphisms were also found to contribute to elevated IRF4 expression in cells from multiple myeloma patients." (PMID 30515152, 2018). "Overexpression of IRF4 has been implicated in oncogenicity in multiple myeloma, the activated B cell-like subtype of diffuse large B cell lymphomas, primary effusion lymphoma and peripheral T-cell lymphomas." (PMID 28910419, 2017). "Our results show that IRF4 is overexpressed in melanoma, in addition to previously reported contexts including leukemia, myeloma, and lymphoma, and that IRF4 is associated with a unique gene expression pattern in each context." (PMID 25207815, 2014). "IRF4 is critically involved in tumorigenesis and the immune system, with its dysregulated expression closely linked to the development of autoimmune diseases, lymphomas, multiple myelomas and other malignancies." (PMID 39609883, 2024). "Notably, IRF4 translocation to actively transcribed genomic areas in some multiple myeloma (MM) patients is associated with carcinogenicity and overexpression, yet it confers a survival benefit in MM without translocations or amplifications." (PMID 38792604, 2024).
myeloma (continued). "This is contrary to the finding that knockdown of IRF4 in myeloma can induce apoptosis of myeloma cells, which may be caused by disease models and different cells." (PMID 39609883, 2024). "Instead, IRF4, an important regulator of the immune response, has been shown to be associated with many lymphoid malignancies with evidence pointing to a pivotal role in multiple myeloma." (PMID 35870994, 2022). "Inappropriately heightened IRF4 activity is a hallmark of myeloma genesis." (PMID 34793338, 2021). "We also detected additive loss of IKAROS/IKZF1 and the myeloma pro‐survival factors IRF4 and FOXM1." (PMID 31714026, 2020). "Finally, the lncRNAs expressed specifically in TPCs were related to genes upregulated in plasma cells, targets of IRF4, and associated with multiple myeloma (MM)." (PMID 30778059, 2019). "Its T-variant is known to be associated with lower expression levels of the IRF4 gene, which means that it could potentially affect not only pigmentation-related diseases, but also other ones, such as multiple myeloma." (PMID 28083618, 2016). "Previously, IRF4 positivity in immunohistochemical staining had a significant correlation with increased disease stage in multiple myeloma, and its silencing caused cell death in myeloma cell lines." (PMID 27223072, 2016). "Enhanced expression of IRF4 is often associated with multiple myeloma and adult T-cell lymphomas." (PMID 23658517, 2013). "Both downregulate IRF4, a key target and master transcriptional factor regulating myeloma cell survival." (PMID 40805136, 2025). "Both IBR and LEN downregulate a master transcriptional factor, IRF4, that mediates myeloma cell survival, and disrupts bone marrow stromal support." (PMID 40805136, 2025). "It is paramount to note that the IRF4 gene correlates with several hematological malignancies, including multiple myeloma, chronic lymphocytic leukemia, and non‐Hodgkin lymphoma." (PMID 40134047, 2025). "HTOL was found to block the IRF4 signaling pathway, leading to an arrest in the development of myeloma cells." (PMID 38792604, 2024). "MYC and IRF4 form an autoregulatory circuit in multiple myeloma, where they induce each other’s transcription to promote MM cell growth and survival." (PMID 38911853, 2024). "Based upon the finding that MIDN promoted proteasome-mediated degradation of IRF4, and reports that IRF4 promoted c-Myc expression necessary for myeloma cell survival, we analyzed IRF4 and c-MYC levels in MidnKD/KD splenic B cells by immunoblot." (PMID 38625151, 2024). "In obesity-associated multiple myeloma, ACSS2 stabilises interferon regulatory factor 4 (IRF4) and aids in gene transcription through acetylation." (PMID 38610991, 2024). "Genes involved in B-cell lineage differentiation are frequently mutated in multiple myeloma, including PRDM1 and interferon regulatory factor 4 (IRF4), a key driver of MM5,8,9." (PMID 37081258, 2023). "ACSS2-mediated IRF4 acetylation results in the elevation of IRF4 protein level due to dysregulation of p62-mediated lysosomal degradation in myeloma." (PMID 38060103, 2023). "Then, we describe the unique role of IRF4 in acute leukemias and B cell mature neoplasia, focusing on biological mechanisms and possible therapeutic strategies in multiple myeloma (MM) and chronic lymphocytic leukemia (CLL)." (PMID 36495369, 2023). "In myeloma cells, interferon regulatory factor 4 (IRF4), a transcription factor for myeloma cell growth, is suppressed via the degradation of Ikaros family zinc finger 1/3 (IKZF1/3), inducing a direct anti-myeloma effect." (PMID 38004369, 2023). "In some instances, cells depended strongly on the lineage factor, for example PAX8 in RCC, MITF in melanoma, and IRF4 in multiple myeloma (MM)." (PMID 37554444, 2023). "Other cancers, such as multiple myeloma, have been shown to be dependent on IRF4, and in this context depletion of IRF4 or treatment with an IRF4 inhibitor has been shown to induce lethality." (PMID 36219477, 2023).
myeloma (continued). "DOT1 Like Histone Lysine Methyltransferase (DOT1L), which catalyzes methylation of histone H3 lysine 79, has been reported to be required for myeloma cell survival through enhancing IRF4-Myc signaling." (PMID 35338347, 2023). "Treatment of adipocyte-secreted angiotensin II enhanced the expression of ACSS2 in myeloma cells, which promotes tumorigenesis by maintaining the stability of interferon regulatory factor 4 (IRF4), an oncogenic protein." (PMID 38060103, 2023). "Utx/BrafV600E plasma cells before and after overt MM showed gradual up-regulation and down-regulation of DEGs, including representative myeloma signature genes with upregulation of Myc, Ccnd2, E2f3, and Irf4 and downregulation of Cd19 and Ikzf3." (PMID 37198323, 2023). "Treatment-induced protein expression of the phenotypic/functional markers of myeloma (p65/NFκB, IRF4, and cMyc) and markers of apoptosis (including Cleaved Caspase-3, Cleaved Caspase-9, etc.)was confirmed using immunoblotting analysis in HMCLs." (PMID 35264575, 2022). "SuperDendrix also finds associations for three downstream targets of TCF3 and IRF4 transcription factors: BCL2 and {leukemia, myeloma, MEF2B(A)}, PIM2 and myeloma, and POU2AF1 and Myeloma,MEF2BA." (PMID 35382456, 2022). "Taken together, these results show increased dependency on the B cell lineage-specific transcription factors in blood cancers, with cancer-type-specific addiction to TCF3/IRF4 regulatory pathway in myeloma mediated by MYC expression." (PMID 35382456, 2022). "The ACSS2-IRF4 complex was found in myeloma using co-immunoprecipitation, and the knockdown of ACSS2 decreased the function of IRF4 and significantly inhibited the growth of myelomas." (PMID 35740562, 2022). "TCF3 and IRF4 have previously been suggested as dependencies in myeloma and are part of the core regulatory circuitry, promoting tumorigenesis in cooperation with aberrant MYC activity." (PMID 35382456, 2022). "We and others showed that super-enhancers were associated to key genes contributing to myeloma pathogenesis, such as MYC, IRF4, CCND1, NSD2 and MAF39,66." (PMID 35198065, 2022). "Another set of curcumin analogs GO-Y078 and GO-Y030 were discovered to be 7 to 12-fold more potent growth inhibitors for myeloma cells, and 6- to 15-fold more powerful suppressors of IRF4, JAK/STAT3, PI3K/AKT, and NF-κB pathways than curcumin." (PMID 36386899, 2022). "Computed tomography imaging revealed a monostotic osteolytic bone-lesion, and bone marrow cytology and histopathology documented plasmacytosis with multiple myeloma oncogene 1 / interferon regulatory factor 4 positivity, consistent with multiple myeloma." (PMID 36125290, 2022). "Inhibitors of ACSS2 can be used to accelerate its degradation and thus reduce the level of IRF4 and inhibit the growth of myelomas." (PMID 35740562, 2022). "Dependencies on POU2AF1 and PIM2, the target genes of TCF3 and IRF4 transcription factors, suggest cancer-type-specific addiction to transcriptional regulatory pathway in myeloma." (PMID 35382456, 2022). "Studies show that inhibition of EZH2/G9a upregulates interferon (IFN)-stimulated genes and suppresses IRF4-MYC axis genes in multiple myeloma." (PMID 35409271, 2022). "Most important of these are IKZF1 and IKZF3, key MM survival transcription factors which sustain the expression of myeloma oncogenes IRF4 and MYC." (PMID 36439455, 2022). "For example, IFI27 involves in the IRF4 regulatory network, which is implicated in MDS, leukemia, myeloma and lymphoma." (PMID 36713414, 2022). "In the case of MEF2C, the set of its predicted target TF, includes archetypical myeloma PC dependencies, i.e., IRF4, PRDM1, thus in part explaining the high degree of myeloma cell dependency on MEF2C." (PMID 34521827, 2021). "Although IRF4 functions as a tumor suppressor gene in early B-cell development, in multiple myeloma IRF4 is a well-established oncogene,with oncogenic implications extending to adult leukemias and lymphomas, as well as pediatric leukemia." (PMID 34220922, 2021).
myeloma (continued). "The current disease researched on IRF4 mostly focuses on multiple myeloma, lymphoma, and various subtypes of leukemia." (PMID 34020619, 2021). "HDAC11 inhibition, likely via its inactivation of IRF4, delivers a cytotoxic insult to myeloma cells in vitro." (PMID 34793338, 2021). "Inhibition of EP300/CBP causes acute repression of IRF4 and MYC in myeloma cells, further indicating that MM cells are strongly dependent on these two key transcription factors." (PMID 34834536, 2021). "The transcription factors such as B lymphocyte induced maturation protein 1 (Blimp-1), X-box binding protein 1 (XBP-1), and interferon regulatory factor 4 (IRF4) are critical for myeloma cells differentiation and development." (PMID 34349655, 2021). "Since MYC is a direct target of IRF4 in activated B cells and myeloma, we next evaluated the expression of both proteins after treatment with PIM-Pd over time." (PMID 32987735, 2020). "Although a low level of enrichment of CTCF motifs can be seen at IRF4-bound regions in ABCs and ABC-DLBCL, this is significantly lower than in plasmablasts or myeloma cell lines, suggesting that the association is linked to differentiation." (PMID 32843533, 2020). "IRF4 has been identified as a key driver in other lymphoid malignancies, including multiple myeloma." (PMID 32859220, 2020). "IRF4 is a member of the interferon regulatory family and has emerged as a master regulator in multiple myeloma, controlling a regulatory network to which MM cells are addicted, and that is essential for their survival." (PMID 32211606, 2020). "Another Ets family TF, FLI1, has recently been shown to cooccupy sites with IRF4 in multiple myeloma." (PMID 32843547, 2020). "Lenalidomide inhibits proliferation of multiple myeloma and primary effusion lymphoma at least partially by repressing IRF4 expression." (PMID 32859220, 2020). "IRF4 is a transcription factor, which is necessary for the survival of lymphoma and myeloma cells, leading to an induction of apoptosis in these cells." (PMID 32582706, 2020). "Lenalidomide, an FDA approved drug currently used to treat multiple myeloma and other lymphoid malignancies, indirectly suppresses IRF4." (PMID 32859220, 2020). "IRF4 antisense oligonucleotides were found to possess anti-tumor activity in multiple myeloma, which was also found to be addicted to IRF4 for survival." (PMID 32748879, 2020). "In plasmablasts, IRF4 acquires an association with CTCF, a feature maintained in plasma cell myeloma lines." (PMID 32843533, 2020). "Positive inhibitory effects of this synthetic microRNA have been confirmed in vitro and in vivo, leaving IRF4 as an interesting multiple myeloma therapeutic target." (PMID 31178872, 2019). "Previous evidences revealed that lenalidomide down-regulates IRF4 transcription, connecting this mechanism to the anti-myeloma activity." (PMID 30760870, 2019). "This connected the germline risk of myeloma to a genetic pathway of great significance for myeloma biology: IRF4-MYC." (PMID 31139207, 2019). "IRF4 expression is inversely correlated with clinical outcome of myeloma and IRF4-dependent modulation of Fas-induced apoptosis governs, in part, myeloma survival." (PMID 31139207, 2019). "In myeloma cells, this mechanism is described as an autoregulatory circuit, with IRF4 directly targeting MYC and at the same time IRF4 representing a direct target of MYC transactivation." (PMID 29617304, 2018). "In contrast, dysregulated IRF4 has been implicate in multiple myeloma where its expression was found to correlate with malignancy-specific gene expression." (PMID 30515152, 2018). "The first association with cancer came from the identification of a chromosomal translocation that juxtaposes the immunoglobulin heavy-chain locus to IRF4 in multiple myeloma patients." (PMID 29346274, 2018).